RAB7A (RAB7A, member RAS oncogene family)
Description:
The small GTPases Rab are key regulators of intracellular membrane trafficking, from the formation of transport vesicles to their fusion with membranes. Rabs cycle between an inactive GDP-bound form and an active GTP-bound form that is able to recruit to membranes different sets of downstream effectors directly responsible for vesicle formation, movement, tethering and fusion. In its active state, RAB7A binds to a variety of effector proteins playing a key role in the regulation of endo-lysosomal trafficking. Governs early-to-late endosomal maturation, microtubule minus-end as well as plus-end directed endosomal migration and positioning, and endosome-lysosome transport through different protein-protein interaction cascades. Also plays a central role in growth-factor-mediated cell signaling, nutrient-transportor mediated nutrient uptake, neurotrophin transport in the axons of neurons and lipid metabolism. Also involved in regulation of some specialized endosomal membrane trafficking, such as maturation of melanosomes, pathogen-induced phagosomes (or vacuoles) and autophagosomes. Plays a role in the maturation and acidification of phagosomes that engulf pathogens, such as S.aureus and M.tuberculosis. Plays a role in the fusion of phagosomes with lysosomes. In concert with RAC1, plays a role in regulating the formation of RBs (ruffled borders) in osteoclasts. Controls the endosomal trafficking and neurite outgrowth signaling of NTRK1/TRKA. Regulates the endocytic trafficking of the EGF-EGFR complex by regulating its lysosomal degradation. Involved in the ADRB2-stimulated lipolysis through lipophagy, a cytosolic lipase-independent autophagic pathway (By similarity). Required for the exosomal release of SDCBP, CD63 and syndecan. Required for vesicular trafficking and cell surface expression of ACE2. May play a role in PRPH neuronal intermediate filament assembly (By similarity).
Synonyms: RAB7; CMT2B; PRO2706
Tractability: Small molecule: a structure with a bound ligand is known; a high-quality ligand is known; it has a binding pocket of medium quality. Antibody: UniProt places it where antibodies can reach, with high confidence; its Gene Ontology location is reachable by antibodies, with high confidence. PROTAC: UniProt records ubiquitination sites on it; ubiquitination databases record sites on it; its protein half-life has been measured; a small molecule that binds it is known.
Target class: Enzyme; Hydrolase
Gene: Protein-coding gene on chromosome 3 (128,693,669 to 128,825,942, forward strand). Ensembl gene ENSG00000075785.
Subcellular location: Cytoplasmic vesicle, phagosome membrane; Late endosome membrane; Lysosome membrane; Melanosome membrane; Cytoplasmic vesicle, autophagosome membrane; Lipid droplet; Endosome membrane; Cytoplasmic vesicle; Mitochondrion membrane
Subcellular location (Human Protein Atlas): Lysosomes; Primary cilium transition zone; Cytosol
Pathways (Reactome):
Signal Transduction: CDC42 GTPase cycle; RAC1 GTPase cycle; RAC2 GTPase cycle; RAC3 GTPase cycle; RHOD GTPase cycle; RHOF GTPase cycle; RHOG GTPase cycle; RHOH GTPase cycle; RHOJ GTPase cycle; RHOQ GTPase cycle
Disease: Prevention of phagosomal-lysosomal fusion; Suppression of autophagy
Immune System: MHC class II antigen presentation; Neutrophil degranulation
Vesicle-mediated transport: RAB GEFs exchange GTP for GDP on RABs; TBC/RABGAPs
Metabolism of proteins: RAB geranylgeranylation
Gene Ontology:
Molecular function: G protein activity; GDP binding; GTP binding; GTPase activity; protein binding; retromer complex binding; sterol sensor activity
Biological process: autophagosome assembly; cholesterol homeostasis; early endosome to late endosome transport; endosome to lysosome transport; endosome to plasma membrane protein transport; epidermal growth factor catabolic process; lysosome to ER cholesterol transport; negative regulation of exosomal secretion; phagosome acidification; phagosome-lysosome fusion; positive regulation of exosomal secretion; positive regulation of protein catabolic process; positive regulation of viral process; protein localization to lysosome; protein targeting to lysosome; protein to membrane docking; response to bacterium; retrograde transport, endosome to Golgi; viral release from host cell; endocytosis; lipophagy; negative regulation of intralumenal vesicle formation; phagosome maturation; protein transport
Cellular component: endosome membrane; extracellular exosome; late endosome; late endosome membrane; lysosomal membrane; lysosome; melanosome membrane; mitochondrion; phagocytic vesicle; protein-containing complex; retromer complex; cytoplasmic vesicle; cytosol; lipid droplet; phagocytic vesicle membrane; plasma membrane; secretory granule membrane; autophagosome membrane; bounding membrane of organelle; mitochondrial membrane
Genetic constraint (gnomAD): Loss-of-function variants: 2 observed, 25.99 expected, observed/expected ratio (o/e) 0.077, 90% interval 0.03 to 0.24. The upper end of that interval is the gene's LOEUF score, 0.24, which puts it in group 1 of 6, group 1 being the genes least tolerant of losing a copy. Missense variants: 118 observed, 269.54 expected, observed/expected ratio (o/e) 0.44, 90% interval 0.38 to 0.51. Synonymous variants: 100 observed, 99.88 expected, observed/expected ratio (o/e) 1, 90% interval 0.85 to 1.18.
Gene-disease validity (ClinGen):
ClinGen rates the evidence that RAB7A causes each of these diseases.
Charcot-Marie-Tooth disease type 2 (autosomal dominant): Definitive. A Charcot-Marie-Tooth disease characterized by abnormalities in the axon of the peripheral nerve cell.
Homologues: Orthologues: mouse Rab7 (100% identical), guinea pig RAB7A (99% identical), rat Rab7a (99% identical), zebrafish rab7a (98% identical), pig RAB7A (94% identical), tropical clawed frog rab7a (93% identical), zebrafish RAB7A (89% identical), zebrafish rab7b (87% identical), Drosophila melanogaster Rab7 (77% identical), macaque RAB7A (70% identical). Paralogues in human: RAB9B (50% identical), RAB9A (49% identical), RAB7B (47% identical), RAB5C (40% identical), RAB5A (39% identical), RAB5B (39% identical), RAB31 (38% identical), RAB6A (38% identical), RAB27A (37% identical), RAB6B (37% identical), RAB2B (36% identical), RAB33B (36% identical), and 56 more.
Diseases named in the same sentence as RAB7A in open-access papers:
RAB7A is named in the same sentence as 86 diseases in open-access papers, as found by Europe PMC text mining. Sharing a sentence is not in itself a finding about the gene and the disease. The quoted sentences say what the papers report.
melanoma (10 papers, 2015 to 2025). A malignant, usually aggressive tumor composed of atypical, neoplastic melanocytes. "In highly invasive melanoma cells, this favors invasive phenotypes supporting Rab7a as a risk factor for melanoma metastasis and poor survival." (PMID 33195279, 2020). "Knockdown of Rab7a suppresses the proliferation, migration, and xenograft tumor growth of breast cancer cells and high Rab7a expression is an indicator of a higher risk of metastasis in early melanoma patients." (PMID 39562548, 2024). "RAB7A upregulation has also been observed in melanoma, suggesting enhanced late endosome traffic/function." (PMID 41155412, 2025). "Our data imply that Rab7a acts as an enhancer of TPC2 activity to regulate melanoma proliferation, migration, invasion, and tumor growth." (PMID 39562548, 2024). "We will discuss here the role of TPC2 in pigmentation and its potential to impact melanoma development and progression and highlight recent findings on Rab7a as an enhancer of TPC2 activity." (PMID 39682251, 2024). "We have shown here that knockout of either Rab7a or TPC2 in melanoma lines, in particular those that express high levels of MITF result in similar phenotypes i.e., reduction of proliferation, migration, invasion, and tumor growth in vitro and in vivo." (PMID 39562548, 2024). "Our data provide a new concept of how a small GTPase, Rab7a affects cancer/melanoma hallmarks by controlling the activity of the endolysosomal cation channel TPC2 with effects on GSK3β degradation and thus β-Catenin and MITF levels." (PMID 39562548, 2024). "We have generated TRPML1 KO SK-MEL-5 melanoma cells in addition to previously generated KOs for Rab7a and TPC2 in SK-MEL-5 cells using CRISPR/Cas9." (PMID 39682251, 2024). "We further found that KO of Rab7a reduces endogenous TPC2 activity in SK-MEL-5 melanoma cells, corroborating the findings in OE HEK293 cells." (PMID 39562548, 2024). "Here, the authors show that Rab7a enhances the activity of TPC2 to promote melanoma progression through the GSK3β/β-Catenin/MITF axis." (PMID 39562548, 2024). "In the following, we will discuss the latest on TPC2 and its role in melanoma, as well as its functional interaction with the oncogene Rab7a." (PMID 39682251, 2024). "In sum, these data demonstrate high expression levels of both TPC2 and Rab7a in melanoma and/or melanoma lines while expression levels in other cancer types or control tissue were generally lower." (PMID 39562548, 2024). "Here, we will discuss recent evidence for TPC2 and its effector Rab7a as proteins involved in melanin production and their implications for melanoma development." (PMID 39682251, 2024). "Effects of TPC2 or Rab7a KO or KD on proliferation, migration, and invasion were seen particularly in melanoma lines expressing high levels of MITF, and MITF levels were strongly depleted or reduced after either KO or KD of TPC2 or Rab7a." (PMID 39562548, 2024). "The small GTPase Rab7a, which regulates the fusion between endosomes and autophagosomes with lysosomes, is enriched in melanoma cells where it also is important for sustaining cell proliferation and cancer progression." (PMID 33195279, 2020). "In fact, high expression of RAB7A has been correlated with high production of exosomes in melanoma cell lines and a RAB7A-dependent exosomal pathway has been demonstrated for miR-143 export." (PMID 30626032, 2019). "It belongs to the microphthalmia family of evolutionarily conserved members in the vertebrates, also including TFEC, TFE3, and MITF (microphthalmia-associated transcription factor), whereby the latter one has recently been shown to play a key role in TPC2/Rab7a-driven effects in melanoma cells." (PMID 39682251, 2024). "We next performed TPC2 and Rab7a knockdown (KD) experiments in several other melanoma lines." (PMID 39562548, 2024).
melanoma (continued). "In in vivo experiments in mice, we could show that dissemination and tumor growth/weight were reduced in mice injected with TPC2 KO or Rab7a KO B16F10-luc melanoma cells as compared to WT B16F10-luc melanoma cell injection." (PMID 39562548, 2024). "Furthermore, in melanoma cells Rab7a levels are significantly elevated compared to normal skin melanocytes, impacting melanoma proliferation and invasion." (PMID 39562548, 2024). "Rab7a itself is known as an oncogene with reported roles in cancer and melanoma." (PMID 39682251, 2024). "During melanoma progression, Rab7a expression is then downregulated." (PMID 33195279, 2020). "In particular, at early stages of melanoma development, Rab7a is upregulated and sustains melanoma cell proliferation controlled by the lineage-specific transcription factor SOX10 and the oncogenic transcription factor MYC, which is activated at early stages of melanoma development." (PMID 33195279, 2020). "However, expression and functional analyses of melanoma-enriched endolyososomal factors revealed a particular dependency of this tumor type on the membrane traffic regulator RAB7A." (PMID 26008978, 2015). "Increased expression of Rab7A in human cells, clinical specimens, and mouse models highlighted that this key membrane traffic regulator is an early-induced melanoma driver, to which melanoma become particularly addicted to support their increased invasiveness and metastatic potential." (PMID 27896217, 2016). "In sum, the majority of melanoma lines with high MITF levels responded with a reduction in invasion and proliferation after either TPC2 or Rab7a KD/KO." (PMID 39562548, 2024). "Expression levels (mRNA) of Rab7a and TPC2 are particularly high in melanoma cells including SK-MEL-5 cells, which were chosen to generate knockout (KO) lines for both genes using CRISPR/Cas9 strategies." (PMID 39562548, 2024). "Generally, melanoma lines, which showed reduced proliferation and invasion after either TPC2 or Rab7a KD expressed higher levels of MITF." (PMID 39562548, 2024). "Expression of Rab7a in different cancer types strongly correlates with the expression of TPC2, with expression of both proteins being particularly high in melanoma cells." (PMID 39562548, 2024). "In analogy to TPC2, Rab7a knockdown in NPC1 cells exacerbates cholesterol accumulation, and in melanoma cells, Rab7a levels are significantly higher than in healthy skin melanocytes, impacting melanoma proliferation and invasion." (PMID 39682251, 2024). "As a pathophysiological consequence of the Rab7a mediated effect on TPC2 activity, proliferation, migration and invasion of melanoma cells were found to be reduced after Rab7 KO or knockdown (KD), similar to TPC2 KO or KD." (PMID 39867224, 2024). "As further evidence that components of the GSK3β/MITF axis are affected by Rab7a/TPC2 activity, we demonstrated that β-Catenin is reduced in Rab7a as well as in TPC2 KO melanoma lines." (PMID 39562548, 2024). "CPEB4 is highly expressed in the early stage of melanoma progression; it can control the polyadenylation of the melanoma drivers, MITF and RAB7A, through binding to their 3′-UTRs." (PMID 32967226, 2020). "Essential in these CPEB4-controlled networks are the melanoma drivers MITF and RAB7A, a feature validated in clinical biopsies." (PMID 27857118, 2016). "Based on our data, including data confirming reduced endolysosomal function in Rab7a as well as TPC2 KO SK-MEL-5 melanoma cells for other cells, we postulate that activation of TPC2, enhanced by Rab7a promotes endolysosomal activity and thus degradation of GSK3β." (PMID 39562548, 2024). "Effects on proliferation and invasion in Rab7a KO melanoma cells could be rescued by TPC2 OE and/or TPC2 activation but vice versa TPC2 KO could either not be rescued by Rab7a OE (invasion) or with much reduced rescue efficacy (proliferation)." (PMID 39562548, 2024).
breast carcinoma (6 papers, 2019 to 2025). "RAB7A is highly expressed in breast cancer tissues and promotes cancer cell proliferation and invasion." (PMID 40080350, 2025). "Our statistical analysis of the expression levels of Parkin, Rab1a, and Rab7a proteins in breast cancer tissues (n = 88) indicated that there were significant reciprocal correlations between Parkin and Rab1a, as well as between Parkin and Rab7a." (PMID 40687836, 2025). "mRNA expression of Rab7a was detected in normal breast cell line HMepC and in various breast cancer cells, including ZR-75-30, MCF-7, T-47D, MDA-MB-231, and HCC-1937 cells." (PMID 29769411, 2019). "We suggest that Rab7a inhibits the apoptosis and promotes the proliferation and growth of breast cancer cells." (PMID 29769411, 2019). "In summary, our study provided evidences for the first time that Rab7a functioned as an oncogene in breast cancer." (PMID 29769411, 2019). "We found that Rab7a was up-regulated in breast cancer tissues compared with adjacent normal tissues." (PMID 29769411, 2019). "Altogether, our results highlight the novel function of Rab7a in the proliferation, invasion, and xenograft tumor development of breast cancer cells." (PMID 29769411, 2019). "Ras-related protein Rab-7a (Rab7a) is involved in late endocytic trafficking, while its role in breast cancer is largely unclear." (PMID 29769411, 2019). "To investigate the clinical relevance of Rab7a in breast cancer, we collected breast cancer samples and checked Rab7a expression by immunohistochemical staining." (PMID 29769411, 2019). "Since vimentin is biomarker of epithelial–mesenchymal transitions, which play a crucial role in cancer metastasis, we attempted to investigate the role of Rab7a in breast cancer cell migration." (PMID 29769411, 2019). "Our findings that Parkin mediates ubiquitination of these oncogenic Rabs and decreases their expression in the cell, as well as the reciprocal correlations between Parkin and Rab1a or Rab7a in breast cancer tissues, reiterate the role of Parkin as a tumor suppressor." (PMID 40687836, 2025). "Thus, the RAB5/RAB7A/GDI2 subnetwork regulates αVβ6-HER2 cross-talk to drive breast cancer invasion but is subverted in trastuzumab-resistant cells to drive αVβ6-independent and HER2-independent tumor progression." (PMID 39630893, 2024). "Liensinine affects the dephosphorylation and mitochondrial metastasis of DNM1L, which inhibits the recruitment of RAB7A to lysosomes, thereby blocking autophagosome–lysosome fusion and enhancing doxorubicin-mediated apoptosis, ultimately reducing the activity of breast cancer cells." (PMID 34065886, 2021). "We found that Rab7a mRNA level was higher in these breast cancer cells comparing with HMepC cells." (PMID 29769411, 2019). "Overall, Rab7a was critical for breast cancer cell survival and metastasis." (PMID 29769411, 2019). "In the present study, we investigated the role of Rab7a in breast cancer." (PMID 29769411, 2019). "Breast cancer tissues showed enhanced Rab7a expression compared with adjacent breast tissues." (PMID 29769411, 2019). "Next, we analyzed the effect of Rab7a silencing on breast cancer cell viability." (PMID 29769411, 2019). "In the present study, we identified Rab7a as a novel biomarker for breast cancer." (PMID 29769411, 2019). "In this study, we first found that Rab7a was up-regulated in breast cancer tissues and cells." (PMID 29769411, 2019). "Comparing with adjacent breast tissues, Rab7a expression was increased in breast cancer tissues." (PMID 29769411, 2019). "We showed that Rab7a knockdown blunted the invasion capacity of breast cancer cells." (PMID 29769411, 2019). "Collectively, Rab7a is a potential biomarker for breast cancer." (PMID 29769411, 2019). "In addition, Rab7a silencing also caused reduced expression of RPS6KB1, which has been reported to be altered in breast cancer tissues." (PMID 29769411, 2019).
breast carcinoma (continued). "In the present study, eIF4E was down-regulated by Rab7a knockdown, suggesting that Rab7a might promote breast cancer through regulating eIF4E." (PMID 29769411, 2019). "Targetting Rab7a might be a potential therapeutic strategy for breast cancer." (PMID 29769411, 2019). "Thus, we used KD2 cell lines to investigate the role of Rab7a in breast cancer development." (PMID 29769411, 2019). "To determine the role of Rab7a in breast cancer, we silenced Rab7a using lentivirus-mediated knockdown strategy in MDA-MB-231 breast cancer cells." (PMID 29769411, 2019).